IL18 (interleukin 18)
Diseases named in the same sentence as IL18 in open-access papers (continued):
Sharing a sentence is not in itself a finding about the gene and the disease.
atopic dermatitis (continued). "In addition, GSK1070806, a humanized antibody targeting IL-18, is currently being tested in a phase 1 trial for atopic dermatitis (ClinicalTrials.gov Identifier: NCT04975438)." (PMID 34831246, 2021). "Similarly, anti-IL-18 antibodies inhibit the development of atopic dermatitis and asthma-like phenotypes in mouse models." (PMID 30992532, 2019). "It was reported that a deficiency of IFN-γ production in severe atopic dermatitis (AD) patients could not be reversed by IL-18 in vitro." (PMID 23283012, 2009). "High serum levels of IL-18, IL12/p40 and IgE antibodies have been found in individuals with atopic eczema and their serum levels correlate proportionally with clinical severity of AE skin lesions." (PMID 33552997, 2020). "Paramylon has been shown to improve the symptoms of atopic dermatitis and decrease the secretion of IL-4, IFN-γ, IL-18, and IL-12 in NC/Nga mice." (PMID 29389956, 2018). "Regarding allergy, interestingly IL-18 contributes to the spontaneous development of IgE/signal transducer and activator of transcription (STAT6)-independent atopic dermatitis-like inflammatory skin lesion." (PMID 22876248, 2012). "Biomarkers for atopic dermatitis, including CTACK (strong correlation), IL-18 (strong correlation), and IgE (moderate correlation), were also increased, although the patient had no obvious clinical manifestations of atopic dermatitis." (PMID 37404820, 2023). "Moreover, monoclonal antibodies targeting IL-18, such as GSK-1070806 and camoteskimab, are currently under development for conditions like atopic dermatitis and Still’s disease, and may hold potential for therapeutic evaluation in SLE." (PMID 41436137, 2025). "The latest studies confirm the expression of IL-33 receptors in atopic dermatitis, but indicate that IL-18 may be of key importance in maintaining the independence of IL-33 activation of ILC2 during skin inflammation, hence the low effectiveness of IL-33 inhibition in atopic dermatitis." (PMID 38672221, 2024).
Cirrhosis (40 papers, 2012 to 2025). A chronic disorder of the liver in which liver tissue becomes scarred and is partially replaced by regenerative nodules and fibrotic tissue resulting in loss of liver function. "In clinical studies, the expression level of IL-18 in the peripheral serum of patients with hepatitis B-associated cirrhosis complicated by hepatorenal syndrome (HRS) was significantly higher than in patients without this complication." (PMID 39995661, 2025). "Genetically, IL-18 variants, resulting in higher IL-18 levels, were significantly associated with chronic liver diseases (including cirrhosis) in the overall population." (PMID 36313762, 2022). "Additionally, another study suggested a potential association between the IL-18 -137G/C gene variant and the risk of cirrhosis susceptibility." (PMID 39995661, 2025). "A study explored the impact of genetic polymorphisms (IL-18, IFN-c, and IL-10) on the risk of cirrhosis in chronic hepatitis C patients." (PMID 40165825, 2025). "A similar trend was observed for CD4+ T cells, where TNFα expression was downregulated after stimulation with IL-12 + IL-18 in compensated cirrhosis compared to healthy controls." (PMID 41028194, 2025). "The study concluded that L-FABP, along with three other biomarkers (NGAL/Neutrophil gelatinase-associated lipocalin, IL-18/Interleukin-18, and albumin), has a good and efficient ability to differentiate patients with progressive AKI and cirrhosis." (PMID 38136624, 2023). "Cytokine levels of IFN-α2, IFN-γ, TNF-α, IL-6, IL-8, IL-10, IL-17A, IL-18, IL-23, and IL-33 were significantly elevated in patients with decompensated cirrhosis compared to patients with compensated cirrhosis." (PMID 38077228, 2023). "This study indicates that IL-18 -137GG genotype carriers were more likely to develop cirrhosis than CC carriers." (PMID 37101651, 2023). "Several studies have shown that in patients with cirrhosis, urinary IL18 concentrations vary depending on the type of the kidney injury." (PMID 38139297, 2023). "Plasma levels of IL-18 and IL-18BP were elevated in chronic liver diseases such as cirrhosis, correlating with inflammation, liver injury and severity of the disease." (PMID 36313762, 2022). "Currently, some published studies found that urinary NGAL and urinary IL-18 can be used as a biomarker to identify the differentiating ATN from HRS and other causes of AKI in cirrhosis." (PMID 35784735, 2022). "Urine levels of IL-18 and lipocalin-2 from patients with cirrhosis discriminate between those with ATN and other types of kidney impairments." (PMID 34831270, 2021). "The usefulness of biomarkers such as Neutrophil Gelatinase Associated Lipocalin (NAGL), interleukin-18, kidney injury molecule-1, and L-FABP have been studied in patients with cirrhosis." (PMID 34640346, 2021). "Although NGAL and IL-18 have demonstrated their usefulness in predicting the prognosis of cirrhosis patients and in patients with acute-on-chronic liver failure, both markers are not widely used in clinical practice." (PMID 34640346, 2021). "In the Child–Pugh class of decompensated cirrhosis, urinary lipocalin-2/IL-18 levels increased and GFR decreased significantly." (PMID 34831270, 2021). "Belcher and colleagues evaluated changes of kidney biomarkers, such as NGAL, KIM-1 and interleukin 18, in the differential diagnosis of patients with cirrhosis and AKI." (PMID 32808849, 2020). "The changes found in nitrates, plasma cGMP, basal cGMP in lymphocytes and SNAP-induced cGMP increase, as well as IL-6, IL-18 and ammonia, were consistent with described changes in cirrhosis." (PMID 26420028, 2015). "In conclusion, urinary NGAL and urinary IL-18 have the ability to differentiate between AKI types in patients with cirrhosis." (PMID 24967242, 2014). "Urinary NGAL and urinary IL-18 have the ability to differentiate between AKI types in patients with cirrhosis." (PMID 24967242, 2014).
Cirrhosis (continued). "The sensitivity and specificity of IL-18 for predicting HRS were 90.32% and 71.70%, respectively, suggesting that IL-18 could predict the prognosis of patients with hepatitis B-related cirrhosis." (PMID 39995661, 2025). "Cumulating data indicate that IL-18 may influence the clearing of the viral load, as well as the severity of the infection in some cases of hepatic carcinomas or cirrhosis." (PMID 27027876, 2016). "Therefore, this study was to assess the ability of urinary NGAL and IL-18 as early biomarkers of AKI in patients with cirrhosis." (PMID 24967242, 2014). "Increased levels of C-C motif chemokine ligand 2 (CCL2), interleukin (IL)-18, IL-33, and citrullinated histone H3 (CitH3)—an accurate marker of neutrophil extracellular traps (NETs)—were detected in the circulation of patients with acute infection or early cirrhosis." (PMID 40565198, 2025). "Many advanced and useful diagnostics, like speckle strain echocardiography, PoCUS, NGAL or IL-18 assays, and even interventions like TIPS, are unavailable or unaffordable in low- and middle-income regions, where the burden of cirrhosis is highest." (PMID 41555935, 2025). "We observed that C-C motif chemokine ligand 2 (CCL2), interleukin (IL)-18, and interleukin (IL)-33 were elevated in the circulation of patients with either acute infection (a-HBV) or early cirrhosis (cir-HBV), in contrast to healthy individuals (HI)." (PMID 40565198, 2025). "Quantitative PCR revealed that FMT from HBV-cirrhosis patients upregulated the hepatic mRNA expression of inflammatory cytokines, including IL-6, TNF-α, and IL-18." (PMID 40642988, 2025). "Patients with cirrhosis and ATI exhibit markedly elevated IL-18 levels in comparison to other etiologies of renal damage." (PMID 40868897, 2025). "Macrophage-CD9/IL18 expanded from HBV infection to cirrhosis, while macrophage-CD9/IFI6 expanded from cirrhosis to HCC." (PMID 38116005, 2023). "In hepatitis C virus infection, studies show that serum IL-18 and IL-1β concentrations are higher in patients with chronic HCV infection and HCV-related cirrhosis compared with healthy controls." (PMID 34161370, 2021). "Nevertheless, several studies have identified close relationships between an individual’s IL-18 haplotype and hepatitis C virus (HCV) and hepatitis B virus clearance, cirrhosis development, and response to treatment." (PMID 31660404, 2019). "Recently, serum IL-18 and IL-1β levels have been observed to be clearly higher in patients with chronic HCV infection and HCV related cirrhosis than in healthy controls, and IL-18 was taken as marker of the acute phase of HCV infection." (PMID 24400125, 2014). "This may reflect differences in marker kinetics: NGAL and IL-18 are rapidly released in acute tubular injury, whereas KIM-1 elevation may be delayed or less pronounced in the setting of cirrhosis-related ATN." (PMID 41353114, 2025). "Subgroup analyses for IL-10–1082 GA + AA vs. GG, IL-10–1082 AA vs. GG, and IL-18 -137 GG vs. CC were not conducted for each etiology of cirrhosis reported by only one study." (PMID 37101651, 2023). "In this study, we could found that patients with cirrhosis and AKI had higher urinary NGAL, urinary IL-18, urinary KIM-1, and urinary L-FABP compared to patients without AKI." (PMID 35784735, 2022). "Serum IL-18 levels are higher in patients with PBC and are positively correlated with cirrhosis." (PMID 33815355, 2021). "Researches show that chronic liver inflammation may lead to fibrosis and cirrhosis through IL-1signaling.And IFI16 can stimulate cleavage of pro-IL1b and pro-IL18 to the bioactive cytokines.So IFI16 may play a role in the pathogenesis of liver cirrhosis, next step we can further investigate it." (PMID 29743020, 2018). "Some studies found urinary KIM-1, urinary NGAL, urinary IL-18, and urinary L-FABP are helpful to distinguish whether AKI is organic or functional damage in patients without cirrhosis." (PMID 35784735, 2022).
pulmonary fibrosis (40 papers, 2011 to 2026). Chronic progressive interstitial lung disorder characterized by the replacement of the lung tissue by connective tissue, leading to progressive dyspnea, respiratory failure, or right heart failure. "IL-18, a product of inflammatory vesicle activation during lung fibrosis, is associated with poorer fibrosis progression." (PMID 39068486, 2024). "Data from animal studies show that IL-18 can lead to pulmonary inflammation; in humans, IL-18 levels increased in patients with idiopathic pulmonary fibrosis, patients with ILD-associated inflammatory myopathy, and patients with RA-ILD." (PMID 37047772, 2023). "The microbial burden was however associated with baseline IL-1β release as well as AIM2 and IL-18 mRNA expression in lung fibrosis." (PMID 34220810, 2021). "IL-18 has been implicated in induction of fibrosis in idiopathic pulmonary fibrosis and heart inflammation; blockage of IL-18 activity has antifibrotic effects." (PMID 34084749, 2021). "Conversely, other studies suggested a protective role against bleomycin-induced lung fibrosis since IL-18 deficient mice had higher survival rate than wild-type." (PMID 29675024, 2018). "IL-18 has also been associated with idiopathic pulmonary fibrosis and CWP." (PMID 36675056, 2023). "In this study, we reported that IL18-hUCMSCs could significantly ameliorate some symptoms of pneumonia, such as weight loss, death, lung injury, lung fibrosis, and apoptosis of lung cells." (PMID 36707501, 2023). "In parallel, an increase in IL-18 may occur, which leads to either a Th1 response with IL-12 or Th17 response with IL-23, also associated with pulmonary fibrosis." (PMID 33802081, 2021). "IL-18 knockout mice are resistant to bleomycin-induced pulmonary fibrosis and elements of IL-18 signaling are elevated in serum of IPF patients." (PMID 39747171, 2025). "Earlier investigations in transgenic mice have confirmed the indispensable role of AMs in pulmonary fibrosis, alongside the observation of heightened IL-18 levels in cases of pulmonary fibrosis." (PMID 39747171, 2025). "Overall, we show that the P2RX7/NLRP3/IL-18 axis in immune cells is required to limit lung fibrosis progression, highlighting the efficacy in targeting the immune system in this disease." (PMID 38300690, 2024). "Overall, we highlight in this study the ability of the P2RX7/NLRP3/IL-18 pathway in immune cells to inhibit the onset of lung fibrosis by using a positive modulator of P2RX7 that acts selectively in an eATP-rich environment such as fibrotic lung." (PMID 38300690, 2024). "For instance, elevated levels of IL-18, which modulates EMT in a Snail-1-dependent manner, have been implicated in the progression of bleomycin-induced pulmonary fibrosis." (PMID 39457694, 2024). "Our results suggest the possible benefit of an active IL-18 in the pathophysiology of pulmonary fibrosis and warrant analysis of IL-18 as a promising biomarker for predicting outcome in IPF patients." (PMID 38300690, 2024). "Animal studies have shown that IL-18 can induce lung inflammation; in humans, elevated IL-18 levels have been observed in patients with idiopathic pulmonary fibrosis, ILD-related inflammatory myopathies, and RA-ILD." (PMID 39534599, 2024). "Previous studies in animal models and patients with pulmonary fibrosis have found that IL-1β and IL-18 levels were significantly elevated in BALF and BALF macrophages, consistent with pre-existing NLRP3 inflammasome activation." (PMID 38136142, 2023). "IL‐18BP inhibited IL‐18‐mediated epithelial wound repair consistent with effects of IL‐18BP inhibiting EMT changes in the murine lung fibrosis model following bleomycin‐induced injury." (PMID 34194747, 2021). "Neutralization of IL-13 or IFN-γ during Ag plus IL-18 challenges inhibited the combination of eosinophilic infiltration, lung fibrosis, and periostin deposition or the combination of neutrophilic infiltration and airway hyperresponsiveness, respectively." (PMID 34367377, 2021).
pulmonary fibrosis (continued). "First, IL-18BP itself is not the cause of the poor outcomes for IPF; although IL-18BP itself has anti-fibrotic and/or anti-inflammatory activity, its increased expression simply reflects increased expression of IL-18, which can promote lung fibrosis." (PMID 34086758, 2021). "A study showed that IL-18 induced airway hyperresponsiveness and lung fibrosis by IFN-γ and IL-13 production." (PMID 34367377, 2021). "IL-18 is known to have high expression in the fibrotic lung, and bleomycin-induced lung fibrosis can be altered by the inhibition of IL-18 expression." (PMID 34086758, 2021). "IL-18 plays a key role in the pathogenesis of pulmonary inflammatory diseases including pulmonary infection, pulmonary fibrosis, lung injury and chronic obstructive pulmonary disease (COPD)." (PMID 23382928, 2013). "The neutralization of IFN-γ during antigen challenge with antigen plus IL-18 inhibited both lung fibrosis and periostin deposition and both neutrophilic infiltration and airway hyperresponsiveness, respectively." (PMID 23300949, 2013). "Interleukin-18 (IL-18) could downregulate the anti-aging protein Klotho, promoting fibroblast senescence in pulmonary fibrosis." (PMID 41522514, 2026). "IL-18 has also been shown to induce EMT in a model of bleomycin-induced pulmonary fibrosis." (PMID 40119408, 2025). "The P2RX7/IL-18/IFN-γ pathway is downregulated in idiopathic pulmonary fibrosis (IPF)." (PMID 38300690, 2024). "Compared with apoptosis, an immune-silent programmed death, pyroptosis could release IL1β and IL18 which could interact with macrophages and fibroblast and therefore have more a strong effects on mechanism of pulmonary fibrosis." (PMID 36033388, 2022). "Previous findings had reported that silica crystals induce the release of IL-1β and IL-18 and pulmonary interstitial fibrosis through the NLRP3 inflammasomes (tetracycline ameliorates silica-induced pulmonary inflammation and fibrosis via inhibition of caspase-1)." (PMID 36131930, 2022). "Apart from that, interleukin 18 can also promote the secretion of cytokines, such as interferon-γ and interleukin 2 by Th1 cells, which then enhances type 1 hypersensitive responses to delay the further progression of pulmonary fibrosis." (PMID 30719057, 2019). "This may be also due to the limited role played by interleukin 18 in the process of pulmonary fibrosis; thus, the effect of YYYQ on interleukin 18 is less significant." (PMID 30719057, 2019). "Furthermore, many lines of evidence suggest that IL-18 plays a key role in the pathogenesis of pulmonary inflammatory diseases including pulmonary infection, pulmonary fibrosis, lung injury and chronic obstructive pulmonary disease (COPD)." (PMID 23382928, 2013). "In agreement with our results, neutralization of IFN-γ during challenge with antigen plus IL-18 inhibited the combination of eoainophilic infiltration, lung fibrosis, and periostin deposition or the combination of neutrophilic infiltration and airway hyperresponsiveness, respectively." (PMID 22567105, 2012). "It was previously reported that IL-18 and IL-18R may be involved in the pathogenesis of pulmonary fibrosis." (PMID 21943057, 2011). "Even though transcriptomic changes do not always reflect changes in the proteome these encouraging results led us to hypothesize that activation of the P2RX7/IL-18 axis may restrain lung fibrosis progression by promoting an antifibrotic immune microenvironment." (PMID 38300690, 2024). "In addition, there is an increasing interest in the assessment of IL-18 in pulmonary fibrosis." (PMID 35435119, 2022).